C19orf25 (chromosome 19 open reading frame 25)
Synonyms: FLJ36666
Tractability: PROTAC: its protein half-life has been measured.
Gene: Protein-coding gene on chromosome 19 (1,461,143 to 1,479,565, reverse strand). Ensembl gene ENSG00000119559.
Subcellular location (Human Protein Atlas): Intermediate filaments
Gene Ontology:
Molecular function: protein binding
Genetic constraint (gnomAD): Loss-of-function variants: 3 observed, 1.84 expected, observed/expected ratio (o/e) 1.63, 90% interval 0.59 to 1.93. That is too few expected variants to judge how well the gene tolerates losing a copy. Missense variants: 196 observed, 134.29 expected, observed/expected ratio (o/e) 1.46, 90% interval 1.3 to 1.64. Synonymous variants: 91 observed, 63.17 expected, observed/expected ratio (o/e) 1.44, 90% interval 1.22 to 1.71.
Homologues: Orthologues: pig C19orf25 (74% identical), dog C19orf25 (71% identical), guinea pig C19orf25 (70% identical), mouse 2310011J03Rik (62% identical), rat C7h19orf25 (60% identical), zebrafish si:ch73-238c9.1 (42% identical).
Diseases named in the same sentence as C19orf25 in open-access papers:
C19orf25 is named in the same sentence as 1 disease in open-access papers, as found by Europe PMC text mining. Sharing a sentence is not in itself a finding about the gene and the disease. The quoted sentences say what the papers report.
cancer (1 paper, 2023). A tumor composed of atypical neoplastic, often pleomorphic cells that invade other tissues. "We observed variable pan-cancer dependency signatures among the top 10 up- and down-regulated hits from our initial screen and found that only C19orf25 is denoted as ‘commonly essential’ in a pan-cancer ranking scheme." (PMID 36961502, 2023).